MT-TC (mitochondrially encoded tRNA-Cys (UGU/C))
Synonyms: trnC; formerly MTTC
Gene: Mitochondrial transfer RNA gene on chromosome MT (5,761 to 5,826, reverse strand). Ensembl gene ENSG00000210140.
Gene-disease validity (ClinGen):
ClinGen rates the evidence that MT-TC causes each of these diseases.
mitochondrial disease (mitochondrial): Limited.